BMI1 (BMI1 proto-oncogene, polycomb ring finger)
Diseases named in the same sentence as BMI1 in open-access papers (continued):
Sharing a sentence is not in itself a finding about the gene and the disease.
cancer (continued). "The PcG gene BMI1 is upregulated in a variety of cancers, where it correlates with clinical grade/stage and a poor prognosis." (PMID 29212025, 2017). "BMI1 is known for its oncogenic properties in various cancers and is considered as a prognostic marker for breast cancer." (PMID 28655885, 2017). "Although it has been reported that miR-128 downregulates BMI-1 in cancers, miR-128-mediated downregulation of BMI-1 and reduction of the CSC-related characters in PTX-resistant lung CSCs has not yet been tested." (PMID 29299167, 2017). "Our results showed that the cancer expression of stem cell markers BMI1, ALDH1 and CD44 were highly upregulated in human SCCHN and mice SCCHN tissues, and NLRP3 inflammasome was closely associated with those makers." (PMID 28865486, 2017). "Several studies also investigated the prognostic value of Bmi-1 in patients with cancer through a meta-analysis." (PMID 28658153, 2017). "Novel studies are suggesting that BMI1 is involved in the proliferation, senescence and migration of cancer and self-renewal of cancer stem cells (CSCs)." (PMID 29220397, 2017). "The well-established oncogenic roles of Bmi1 have spurred intensive efforts to uncover its potential as a therapeutic target for cancer." (PMID 29200967, 2017). "Many studies showed that miR‐194 is downregulated and functions as a tumor suppressor by downregulating its target genes such as N‐cadherin, AKT2 and BMI1 in a variety of cancers." (PMID 28164432, 2017). "Bmi-1 was related to multiple human cancers which played an indispensable role in maintaining the self-renewal ability of both normal and malignant cancer stem cells." (PMID 28220856, 2017). "Several studies have shown that BMI-1 is highly expressed in various cancer types and plays an oncogenic role by maintaining cancer cell stemness and self-renewal, promoting carcinogenesis, invasion and metastasis (reviewed in reference 12)." (PMID 28968963, 2017). "Microarray analysis-defined 11-gene expression signature of the Bmi1 regulated stemness pathway identifies cancer patients with poor prognosis and increased likelihood of death from cancer." (PMID 28418883, 2017). "Recent studies have revealed that downregulation of Bmi1 enhanced the sensitivity of chemotherapeutic drugs in various carcinomas by regulating oxidative stress and inducing apoptosis." (PMID 27926533, 2017). "BMI1, a core element of the polycomb repressive complex 1, is suggested to have oncogenic activity in a variety of cancers." (PMID 27827373, 2016). "In particular, PcG protein BMI1 promotes cancer stem cell (CSC) phenotype and therapy resistance in cancer cells." (PMID 27105531, 2016). "Collectively, our results revealed that CCL21 can induce cancer stem cell properties and upregulation of Bmi-1, Nanog, and Oct-4 in HCT116 cells." (PMID 27057280, 2016). "PRC subunits such as Bmi1 and Ezh2 are often over-expressed in various cancers and are required for formation and maintenance of CSCs." (PMID 26930714, 2016). "Second, Metformin, a pharmacological AMPK activator and anti-diabetic drug, or ectopic expression of LKB1, diminished expression of Bmi-1 in cancer cells, an event that was reversed by silencing LKB1." (PMID 26717043, 2016). "In order to examine the anti-tumor effect of Bmi-1 shRNA for cancer cells, we engineered recombinant adenoviral vectors carrying Bmi-1 shRNA driven by Bmi-1 promoter (Ad-Bmi-1i)." (PMID 27009837, 2016). "BMI1 levels are also elevated in various solid tumor-forming cancers, among them neuroblastoma and bladder cancer." (PMID 27225481, 2016). "Bmi-1 is aberrantly activated in various cancers and plays a vital role in maintaining the self-renewal of stem cells." (PMID 27009837, 2016).
cancer (continued). "The increased incidence of HGPIN/cancer observed in the proximal prostate at 2 months post-tamoxifen treatment suggests that either proximal Bmi1+ cells are more susceptible to Pten-loss induced transformation, or may simply reflect the higher density of Bmi1+ cells in the proximal region." (PMID 27703144, 2016). "Our previous study showed that inhibition of Bmi-1 by its short hairpin RNA (shRNA) inhibited the malignant phenotypes in cancer cells." (PMID 27009837, 2016). "When overexpressed in various cancer types, the BMI1 protein induces cell growth and promotes tumor growth in vitro and in vivo." (PMID 27550987, 2016). "Recent studies have revealed that Bmi1 has a role in regulating the self-renewal of both normal and cancer stem cells (CSCs)." (PMID 26926789, 2016). "We also showed that inhibitors of polo-like kinase 1 (PLK1) can upregulate miR-200c/141 cluster, which indirectly results in downregulation of BMI1 and cancer stem cell phenotype." (PMID 27105531, 2016). "Bmi1 functions as an oncogene and promotes the survival of cancer cells via regulating multiple growth-regulatory pathways." (PMID 27177084, 2016). "B cell-specific Moloney murine leukemia virus integration site 1 (Bmi-1) plays an important role in regulating stemness in some kinds of cancer." (PMID 27644439, 2016). "Previous studies have shown that Bmi-1 protein is overexpressed in different types of human cancers, such as lung, gastric, and breast cancers and leukemia." (PMID 26717043, 2016). "The Cancer Atlas feature was interrogated to assess the antibody staining of YY1, SOX2, OCT4, NANOG and BMI1 in different cancer types." (PMID 27225481, 2016). "Aberrant expression of Bmi-1 has been found in several human cancers and its overexpression is often correlated with poor prognosis in many types of cancers." (PMID 27009837, 2016). "YY1 frequency of expression was associated with the SOX2, BMI1 and OCT4 frequency of expression across many cancers, though the type of association varied." (PMID 27225481, 2016). "miR-200c has been linked with tumor progression and resistance via down-regulation of Bmi-1 in various cancers." (PMID 26894855, 2016). "Our results demonstrated that Twist-induced EMT and tumor-initiating capability in cancer cells occur through direct regulation of the polycomb group protein BMI1, which is involved in the self-renewal of neuronal, haematopoietic, and intestinal cells." (PMID 26823670, 2016). "As an oncogene, Bmi1 is abundantly expressed in many kinds of cancers and is correlated with multiple behaviors including tumorigenicity, drug resistance and cancer recurrence." (PMID 27177084, 2016). "It has been demonstrated that Bmi-1 can regulate the proliferation and clonal growth of tumor cells in a number of malignant tumors." (PMID 26894855, 2016). "Growing evidences suggest BMI1 plays a vital role in regulating self-renewal of normal and cancer stem cells." (PMID 26349457, 2016). "Overexpression of BMI1 has been observed in several human malignancies, including HCC, and BMI1 acts as an oncogene in some cancer types." (PMID 26919246, 2016). "Twist1 plays a crucial role in epithelial-mesenchymal transition (EMT), metastasis, and cancer stemness through direct regulation of BMI1." (PMID 26823670, 2016). "In the present study, we attempted to depict the linear relationship of AMPK, LITAF and Bmi-1 in cancer cells." (PMID 26717043, 2016). "Meanwhile, Bmi1 has also been reported to activate the NF-κB signaling pathway and participate in the cancer progression." (PMID 27177084, 2016). "BMI1 (B cell-specific Moloney murine leukemia virus integration site 1) is a polycomb group family member and emerging data support an important role for BMI1 in cancer." (PMID 27827373, 2016). "Similar results were also found for HGC-27 cancer cells, suggesting that Bmi-1 interference by Ad-Bmi-1i infection also inhibits tumor growth by inducing both cellular senescence and apoptosis in vivo." (PMID 27009837, 2016).
cancer (continued). "Aberrant expression of Bmi1 has been reported to activate multiple growth-regulatory pathways and confer anti-apoptotic abilities to many cancer cells." (PMID 27177084, 2016). "BMI1 pseudogene, namely BMI1P1, located on human chromosomal band Xq12, which has high homology with BMI1, has barely been studied in any cancers." (PMID 27329719, 2016). "Several studies have shown that Bmi-1 RNA interference (RNAi) can inhibit proliferation of cancer cells and increase chemosensitivity." (PMID 27009837, 2016). "Altogether, our data for the first time depicted a regulatory axis sequentially tethering AMPK-LITAF-miRNAs-Bmi-1 in cancer cells." (PMID 26717043, 2016). "Our results showed that AMPK activation increased the abundance of LITAF and concurrently reduced expression of Bmi-1, while knockdown of LITAF upregulated Bmi-1 and promoted aggressive behaviors of cancer cells." (PMID 26717043, 2016). "High levels of the PRC1 components Bmi1 and Ring1b and the strong repression of differentiation genes in 3D-ADMs and cancer cells let us suppose that PRC1 is directly involved in acinar gene regulation." (PMID 26716510, 2016). "Under therapies with genotoxic agents, BMI1 promotes resistance via elevating DSB repair; when required to stimulate cancer progression, BMI1 contributes to genome instability." (PMID 26425649, 2015). "Western blotting and immunofluorescence showed that ablation of Bmi-1 expression restored the Hes1-induced EMT phenomenon in cancer cells." (PMID 26452029, 2015). "Taken together, our results demonstrated a novel miR-494-mediated cancer stemness effect through on the regulation of Bmi1 and ADAM10 expression." (PMID 26090866, 2015). "BMI1 has recently been shown to be upregulated in a variety of human cancers, including brain, breast, prostate, colon, and OSA." (PMID 26110620, 2015). "Aberrant overexpression of Bmi1 is correlated with advanced stages, aggressive clinicopathological behavior, chemotherapeutic resistance and poor prognosis in a variety of cancers." (PMID 25915207, 2015). "By inspecting the human exitron list, we found that EIS affects several cancer-related genes: the cancer marker genes BMI1, KRT5, and MUC1 and the genes involved in cell adhesion (CSF1), migration and metastasis (ZEB2 and KLF17)." (PMID 25934563, 2015). "In order to further elucidate the effects of BMI1-siRNA on cancer cell proliferation, we used EdU incorporation assay to determine the effects of BMI1 on ESCC cell proliferation." (PMID 25999024, 2015). "Another oncoprotein reported to be implicated in the self-renewal regulation of both normal and cancer stem cells is Bmi1." (PMID 25708542, 2015). "In the present study, SB suppressed HNC cancer stemness via enhancing miR-494-mediated suppression of Bmi1 and ADAM10." (PMID 26090866, 2015). "Bmi1 plays a critical role in maintaining the self-renewal capacity of cancer stem cells, which is increasingly recognized to largely account for cancer progression and therapeutic resistance and disease relapse." (PMID 25915207, 2015). "BMI1 is a Polycomb group epigenetic gene silencer that is highly expressed in various types of human cancers." (PMID 25726526, 2015). "Bmi1 is usually upregulated in cancer and its expression was shown to be important for cancer initiation and progression, and maintenance of the CSC compartment." (PMID 25708542, 2015). "Previous reports have showed that Bmi-1 promotes drug resistance and cellular invasion in cancer cells and cancer stem cells, moreover, Hes1 is a well known key apoptosis-inhibiting genes." (PMID 26452029, 2015). "The Polycomb gene Bmi1 is extensively studied in stem cells and rapid dividing cells, such as cancer cells and lymphocytes." (PMID 25611380, 2015). "BMI1 has been shown to be a target of other miRNAs, including miR-128, miR-15a and miR-203 and these miRNAs regulate cancer cell proliferation, differentiation and invasion." (PMID 25999024, 2015).
cancer (continued). "BMI1 plays critical roles in maintaining the self-renewal of hematopoietic, neural, intestinal stem cells, and cancer stem cells (CSCs) for a variety of cancer types." (PMID 26633535, 2015). "Bmi-1 was shown being involved in tumor initiation, self-renewal, and metastasis in malignant carcinomas including HNC." (PMID 26090866, 2015). "To date, only E2F1 and MYCN have been shown to be direct activators of Bmi1 transcription in some kinds of cancers, and data regarding Bmi1 in tumor biology are far from complete." (PMID 24559156, 2014). "Many studies have now conclusively shown that Polycomb proteins and in particular Bmi1 play critical role in regulating self-renewal and proliferation of both normal and cancer stem cells of various tissues." (PMID 25348805, 2014). "A striking finding in recent studies is that the activity of Bmi1 is indispensable for cell survival and self-renewal of stem cells or cancer stem cells." (PMID 24559156, 2014). "These genes control the characters of invasion, migration and proliferation and thus BMI-1 have been implicated as proto-oncogenes and E2F3 the transcriptional factor attractive therapeutic targets against cancer." (PMID 25367080, 2014). "Bmi1 is a member of the polycomb group family of proteins, and it drives the carcinogenesis of various cancers and governs the self-renewal of multiple types of stem cells." (PMID 25372945, 2014). "Previous research indicated that the expression of 3 cancer stem cell markers, aldehyde dehydrogenase 1 (ALDH-1), B cell-specific Moloney murine leukemia virus integration site 1 (Bmi-1), and Nanog, are associated with esophageal cancer." (PMID 25148045, 2014). "The regenerative response is ultimately controlled by BMI1 expression within normal or cancer progenitor cells." (PMID 25277175, 2014). "The role of Bmi1 and the related functional network that serves in regulation of normal cells and cancer cells have been studied extensively in recent years." (PMID 24559156, 2014). "Further studies on Bmi1 mediated regulation of NFκB pathway and Nanog expression in cancer and cancer stem cells would immensely help in understanding the molecular pathways that initiate, drive, and maintain these tumors." (PMID 25348805, 2014). "Several studies have shown that BMI1 is indispensable for self-renewal of normal and cancer stem cells." (PMID 25526772, 2014). "Recent studies have revealed a role for Bmi1 in the regulation of self-renewal in both normal and cancer stem cells." (PMID 25348805, 2014). "High levels of Bmi1 expression were seen in tumorspheres enriched for cancer stem cells which corresponded to the observed elevation in Bmi1 mRNA expression levels on RT-PCR." (PMID 23437065, 2013). "BMI1 is a member of the PcG family of transcription repressors that play crucial roles in development, stem cell biology and cancer." (PMID 24206786, 2013). "Based on our data we suggest that targeting BMI1 should be a part of therapeutic strategy to combat chemoresistant cancer." (PMID 23671559, 2013). "Bmi1 has been identified as a marker of cancer progression in a number of carcinomas, including those derived from the nasopharynx, breast, pancreas, and other sites." (PMID 23592995, 2013). "Bmi1 expression was suppressed by miR-30e* through miR-30e* direct binding to Bmi1 3′ UTR, and Bmi1 expression was inversely correlated with miR-30e* expression in cancer tissues." (PMID 24312366, 2013). "We recently reviewed significance of BMI1 in the emergence of chemoresistance in various types of cancers including CaP." (PMID 23308129, 2013). "Recent studies showed that dysregulation of BMI1 play a crucial role in epithelial mesenchymal transition, cell proliferation, senescence and self-renewability of several human cancers." (PMID 23671559, 2013). "BMI1 is also highly expressed in tumors and regulates the cell fate of cancer cells and normal and tumoral stem cells." (PMID 24206786, 2013).
cancer (continued). "The class of verified anti-apoptotic molecules overexpressed in cancer includes prominent tumor-associated proteins such as β-Catenin (CTNNB1), Osteopontin (OPN/SPP1), BMI1, Peroxiredoxin 3 (PRDX3;) and DAD1." (PMID 23717670, 2013). "However, the mechanism underlying Bmi1 regulation in cancer cells is largely unknown." (PMID 24312366, 2013). "Silencing of Bmi1 inhibited secondary and tertiary tumorsphere formation, decreased primary pancreatic xenograft growth, and lowered the proportion of cancer stem cells in the xenograft tissue." (PMID 23437065, 2013). "BMI1 which has an ubiquitous pattern of expression in almost all tissues is frequently upregulated in various types of human cancers." (PMID 23308129, 2013). "There is a body of evidences suggesting that BMI1 is involved in the proliferation, senescence, migration, and tumorigenesis of cancer." (PMID 23820733, 2013). "We recently reviewed the significance of BMI1 in the emergence of chemoresistance in various types of cancers." (PMID 23671559, 2013). "In our study, Consistent with the reduced metastatic behavior of these cancer cells, the epithelial marker E-cadherin increased in BMI1 siRNA group cells, whereas the mesenchymal marker vimentin and twist decreased." (PMID 23820733, 2013). "Co-culture with TAMs triggered Bmi1 expression in cancer cell lines and enhanced sphere formation ability." (PMID 24312366, 2013). "We next performed an in vitro co-culture assay with M1- or M2-polarized THP-1 macrophages to examine if macrophages affect Bmi1 expression in cancer cells and cancer cell functions." (PMID 24312366, 2013). "Bmi-1 is known to be a useful prognostic marker in many cancers, including nasopharyngeal carcinoma, bladder cancer, gastric cancer, and others." (PMID 23984324, 2013). "Bmi1 protein levels also showed increases in the tumor-derived, telomerase-positive HeLa cancer cell line." (PMID 23592995, 2013). "It is important to note that the expression of BMI-1, the mammalian homolog of Psc, is upregulated in a subset of cancers." (PMID 23893745, 2013). "In this study, we selected microRNAs that were downregulated in cancer cell lines co-cultured with TAMs compared with controls, and identified miR-30e* as binding Bmi1 3ʹ UTR, using in silico prediction methods." (PMID 24312366, 2013). "Bmi1 has been found to sustain cancer stem cell renewal in glioblastoma multiforme and to determine the proliferative capacity of leukemic stem cells." (PMID 23437065, 2013). "Bmi1 was first identified as an oncogene that cooperates with c-myc during mouse lymphomagenesis, and is overexpressed in a variety of human cancers, including gastrointestinal cancer." (PMID 24312366, 2013). "It complements the findings of the other studies and further cements the role of Bmi1 as a key regulator of cancer stem cell renewal, which directly impacts tumor initiation and growth in vivo." (PMID 23437065, 2013). "Bmi-1, a member of the polycomb family, it is involved in self renewal of stem cells and functions as an oncogene in many malignant human cancer types." (PMID 22209830, 2012). "Bmi1 over expression is observed in many types of cancer, including tumors of astroglial and neural origin." (PMID 22574128, 2012). "Self-renewal potential of stem cells has been described to be maintained not only in the haematopoietic lineage but also in neural stem and in cancer cells by the expression of the polycomb gene bmi-1." (PMID 22574183, 2012). "In cancer, both p16INK4A and p19Arf dependent as well as independent oncogenic functions of Bmi1 have been shown." (PMID 22574128, 2012). "In CSCs from various cancers, there is expression of the key ‘stemness’ genes, Oct-4, Bmi1, Notch1, ALDH1, and Sox2." (PMID 22662215, 2012). "Numerous experimental studies have indicated that Bmi-1 plays an important role in the development and progression of cancer and essentially functions as an oncogene." (PMID 22967049, 2012).